TNF (tumor necrosis factor)
Diseases named in the same sentence as TNF in open-access papers (continued):
Sharing a sentence is not in itself a finding about the gene and the disease.
infection (continued). "We also evaluated the levels of four proinflammatory factors (TNF-α, IL-6, IL-1β and IFN-γ) in THP-1 macrophages preincubated with chloroquine (20 μM) or rapamycin (5 μM), followed by infection with Mel+ or Mel˗ S. globosa conidia to activate autophagy." (PMID 37141335, 2023). "Myeloid DCs were present at very low frequencies (<2%), and not more than 70 total cells were detected to be harboring mRNA from TNF, IL6 or IL10 after infection." (PMID 37024448, 2023). "As this cytokine is elevated only at the beginning of canine babesiosis, it seems probable that further control of infection depends on other mechanisms involving IFN-γ and TNF-α, which are triggered by IL-18 together with IL-12." (PMID 36839438, 2023). "Reduced expression of interferon-responsive genes, IL-6, IL-1, IL-1, CCL5, and TNF-, was evidence that TLR3 signaling was downregulated during a live MPOX infection." (PMID 37533932, 2023). "The secretion of cytokines, such as TNF‐α and IFN‐γ, inhibit the replication of bacteria and exosomes carrying antigens can induce the host to produce IgG, resulting in protection against infection." (PMID 37212362, 2023). "Treatment with tumor necrosis factor-alpha (TNF-α) partially restored antimicrobial activity of macrophages from these patients, indicating that this factor contributes to the control of infection." (PMID 37064813, 2023). "Infection of mice with Blimp-1 ablation in T cells resulted failure the cytotoxic CD8+ T cells and in marked Th1-mediated inflammation, high IFN-γ and TNF production, and activation of inflammatory monocyte." (PMID 37908369, 2023). "Interleukin-1 (IL-1), Interleukin-6 (IL-6), Tumor Necrosis Factor-alpha (TNF-α), and Interferon-gamma (IFN-γ) are critical to cytokine storm/CRS resulting from infection/immunotherapy respectively." (PMID 37304291, 2023). "This substantial delay indicates that this was also likely to be a de novo infection, as published data show that LTBI reactivation almost invariably occurs within the first 2 years of starting anti-TNF-α treatment." (PMID 36335186, 2023). "Dpep2 protects mice from inflammatory macrophages in the acute phase by suppressing the activation of the NF-κB pathway to limit the expression of TNF-α, IL-6, and monocyte chemoattractant protein 1 (MCP-1) in response to infection." (PMID 37175422, 2023). "Of note, similar to TNF-α and IL-6, the quantity of IL-27 decreased when TLR-2 or TLR-4 were blocked prior to infection." (PMID 36863206, 2023). "Collectively, these data implicate that in a multi-cellular infection model (3D), CBD and HU308 can decrease viral RNA levels, and that HU308 can reduce IL-1β and TNF-α proinflammatory cytokine mRNA levels." (PMID 37631062, 2023). "Here we show the increase in specific T-cell response, which agrees with the later paper that showed an increase in CD4+TNF-α+ cells in animals immunized with rBCG-LTAK63, fifteen days after H37Rv infection." (PMID 37520577, 2023). "A study by Polari and coworkers described that in the context of human infection by L. braziliensis, the patient’s MΦ increased TLR2 and TLR4 and triggered TNF-α and IL-10." (PMID 37190011, 2023). "In our study, TNF-α and IFN-γ expression was significantly increased during the acute phase of TgCtwh6 infection and decreased during the chronic phase." (PMID 37623985, 2023). "Among critical inflammation and immune response biomarkers, HSP100, TNF-α, TGIF-1, TGIF-2, mCCL22, iNOS, caspase-1, and caspase-8 were significant at different time points in the infection-derived EVs during CCoV infection of CRFK cells." (PMID 36979955, 2023). "Inflammatory cytokines such as IL-6, IL-17, TNF-α, and INF-γ were elevated in infected animals, supporting active infection." (PMID 37512931, 2023).
infection (continued). "Additionally, direct activation of TRPA1 using optopharmacology and chemogenetic methods attenuates TNF production, whereas deletion of TRPA1 or interrupting afferent vagus nerve signaling results in a loss of these anti-inflammatory effects and decreases survival from infection." (PMID 36650454, 2023). "To assess the immunological response of C57BL/6J- Cftrtm1UncTg(FABPhCFTR)1Jaw/J mice to S. maltophilia and P. aeruginosa polymicrobial infection, we measured inflammatory markers in the BALF by multiplex assay for IL-1α, IL-1β, IL-6 and TNF-α." (PMID 36748431, 2023). "More importantly, both SARS-CoV-2 and pCoV-GD01 infection induced the production of cytokines such as IFN-gamma, IL-12p70, IL-13, IL-2, IL-5, TNF-alpha, IL-17A, IP-10, MCP-3, MIP-1beta, MIP-2, Exotaxin, IL-15/15R, IL-28, IL-3, G-CSF, IL-1alpha and ENA-78." (PMID 37330497, 2023). "The mouse neuron cell line NSC-34 was in the trials inoculated with a specified quantity R. helvetica bacteria and the course of the infection was followed by qPCR, immunofluorescence, confocal microscopy, TEM, TNFα assay and Western Blot." (PMID 37085774, 2023). "Infection of BV2 cells with JEV resulted in significant higher expression of IL-6, TNF-α, MCP-1 and IL-1β as compared to un-infected cells." (PMID 36707891, 2023). "At 4 dpi after Omicron BA.2 infection, newly-weaned hamster showed around 10-fold increase of IFN-α, IL-6, and TNF-α, and 4-fold increase of IFN-γ and CXCL10 in brain." (PMID 37122119, 2023). "Infection of APCs with opsonized EBs enhanced expression of chemokines CXCL1, 2, 5 and pro‐inflammatory cytokines IL1β and IFNγ and TNF mRNA." (PMID 38441219, 2023). "Compared to B lineage isolates, infection of mice with UT21 had lower levels of CCL2, CCL3, CCL4, TNF-α, and IL-1β." (PMID 36992320, 2023). "Previous studies have reported that TNF-α increases the expression of CLDN1 in human epithelial cells, and the possibility of increased expression following infection was also mentioned due to the anti-apoptotic effect of CLDN1." (PMID 37799512, 2023). "qRT-PCR revealed that upon T. marneffei infection, mRNA expressions of TNF and CXCL8 were only significantly stimulated in hPBDMs when cultured with the supplementation of autologous plasma during the course of infection." (PMID 37695039, 2023). "In the present study, the two S. parasuis strains sequentially induced the upregulation of IL-6, TNF-α, and MCP-1 gene transcription in the brains of mice with neurological symptoms from 24 h post-infection." (PMID 37111486, 2023). "Data collected 2 h after infection indicated that macrophages infected with Y. pestis pre-incubated with anti-LcrV 7.3 mAb (IgG1) significantly upregulated G-CSF, LIF, MIP-1β, TNF-α, MIP-1α, MCP-3, and MIP-2, while IL-2 and IL-28 were downregulated." (PMID 37289480, 2023). "The activation of TLRs and the subsequent cell signaling lead to the production of pro-inflammatory cytokines, including interleukin-6 (IL-6), interleukin-1 (IL-1), and tumor necrosis factor-alpha (TNF-α), which recruit immune cells to the site of infection." (PMID 37662905, 2023). "Activation of these pathways induces the production of IL-12, tumor necrosis factor (TNF)-α and interferon (IFN) and the recruitment of immune cells such as monocytes, neutrophils and dendritic cells (DC) to the site of infection." (PMID 37077528, 2023). "After 30 days of infection, the production of H2O2 decreased in Swiss mice, as did the production of NO, TNF-α, and IL-10." (PMID 36520787, 2022). "There was also a reduced immune response to infection, which was characterized by lower levels of neutrophil and macrophage infiltration in the lung, and lower levels of cytokines IFN-γ, IL-1β, IL-6, TNF-α, IL-10, IL-12, IP-10, and chemokine CCL2." (PMID 35204727, 2022). "The results showed a significant increase in both mRNA and protein levels of IL-6, IL-1β, and TNF-α in PBMCs and THP-1 cells after SFTSV infection." (PMID 36569095, 2022).
infection (continued). "Upon infection with ZIKV, a release of IL-6 and TNF-α ensues, which has detrimental effects on the fetal brain." (PMID 36300375, 2022). "We found that the serum concentrations of TNF-α and IFN-γ were significantly increased after NE infection when compared to the CON group, although a similar IL-1β concentration was observed." (PMID 35387091, 2022). "Increases the production of IL-10 and reduces the expression of pro-inflammatory IL-12 and TNF-α; stimulates the migration of leukocytes; increases the expression of GM-CSF, IFN-γ, and MCP-1 in the early infection phase." (PMID 36009931, 2022). "These alterations in the kinetics of monocytes, neutrophils, and CD4+ T cells coincided with a significant increase in serum concentration of TNFα, IFNγ, CXCL10, and IL-10 early after infection." (PMID 36466866, 2022). "The level of TNF-a was significantly increased in both the 40 mM and 80 mM L-GSH-treated animals, compared to the untreated group, at 2-, 4-, and 8-weeks post-infection." (PMID 35453358, 2022). "At 7 d post-infection, M4N or ZIL-treated mice displayed increased serum level of TNF-α and MCP-1 while a lower serum level of IFN-γ was observed in ZIL-treated mice." (PMID 36039381, 2022). "The TLR4 signaling pathway can induce cytokine production, such as tumor necrosis factor-alpha (TNF-α) and type I interferon (IFN), B cell proliferation, and maturation of dendritic cells to activate infection defense mechanisms." (PMID 35222098, 2022). "During the infection, Th1 cytokines such as IFN-γ, IL-2 and TNF are essential for supporting the expansion and maturation of CD8+ T lymphocytes and B cells." (PMID 35887351, 2022). "Tumor necrosis factor-α (TNF-α), a representative proinflammatory cytokine produced primarily by macrophages and DCs, is critical for infection control." (PMID 36365041, 2022). "At 10 months post-infection, almost all the enrolled individuals were still positive for SARS-CoV-2-specific IFN-γ- and TNF-α-producing CD4+ T-cells against the M viral protein and for anti-S1 or anti-RBD immunoglobulins." (PMID 34967260, 2022). "Macrophages actively participate in inflammatory responses by releasing pro-inflammatory cytokines: TNF-α, IL-1β, and IL-6 as well as inflammatory cytokines such as NO and PGE2 and recruit additional immune cells to the site of infection or tissue injury." (PMID 35743169, 2022). "A strong interaction between dietary APS and NE infection was observed in relation to TLR2, IFN-γ, TNF-α, IL-6, IL-10, RORα and Foxp3 (P < 0.05) in jejunum." (PMID 35265068, 2022). "Expression of pro-inflammatory cytokines interleukin-6 (IL-6) and tumor necrosis factor-α (TNF-α) in ZIKV spleen at both mid and late disease was two-fold to three-fold higher than pre-infection." (PMID 35876869, 2022). "Production of proinflammatory cytokines TNF-a and IL-6 in mice infected with ∆UDC20 mutant, was significantly higher than those of mice infected with wild-type strain SC84 at 8 h post-infection." (PMID 36031944, 2022). "The mRNA levels of IL-1β, IL-6 and TNF-α were significantly higher in the brains and lungs of ISG15-/- mice as compared with those of WT mice at different time points post infection." (PMID 36315588, 2022). "It cannot be excluded that together with the infection with SARS-CoV-2, additional stimuli—yet to be identified—are needed to induce the secretion of TNF-α from endothelial cells." (PMID 35409421, 2022). "To test how broadly TNFα relies on glycolysis for its antiviral activity in different cell types, we assessed AD169 infection in MRC5 lung fibroblasts, and TB40/e infection, a more recently derived clinical isolate of HCMV, in ARPE-19 retinal epithelial cells." (PMID 35834576, 2022). "This study showed mRNA expression of pro-inflammatory cytokines (IFN-γ, TNF-α, and TGF-β1) significantly upregulated in the infection, similar to IL-10, anti-inflammatory agents commonly used to reduce skin injury." (PMID 35369604, 2022).
infection (continued). "During the early phase of infection (days 1–3 post-infection (p.i.)), the transcription of proinflammatory factors (i.e., IL-12, IFN-γ, TNF-α, IL-1β, IL-6, IL-18) was induced faster under BaP exposure." (PMID 35203386, 2022). "We showed that type II pneumocyte response to infection was characterized by up-regulation of pro-inflammatory genes, including genes whose products are involved in MAPK, TNF, and IL-17 signaling pathways." (PMID 35508983, 2022). "During infection, naïve CD8+ cells release tumor necrosis factor (TNF) and IFNγ and produce cytotoxins (perforins and granzymes), in this way inducing apoptosis." (PMID 36148238, 2022). "The results show a significant upregulated mRNA expression of TNF-α, IL-1β, IL-8 and CCL20 after infection with ETEC as compared to the control condition across both groups." (PMID 36145526, 2022). "A comparative study of cytokine production after influenza virus infection revealed that the production of cytokines such as IL-6, TNF-α, IL-1β, and CCL-2 was delayed and decreased in the early stages of infection in obese subjects." (PMID 36466818, 2022). "Infection with both bacteria and DP1 antagonists significantly reduced the mRNA expression and secretion levels of IL-6, IL-1β, and TNF-α compared with those in the bacteria-only group (P < 0.05)." (PMID 36435808, 2022). "During the last 2 h of infection, JAWS II cells were co-stimulated with E. coli LPS as potent TLR4 ligand to increase TNF-α secretion." (PMID 35910598, 2022). "CD8+ T cells are essential for adaptive immune responses against infection as they secrete cytokines such as interferon-gamma (IFN-γ) and tumor necrosis factor-alpha (TNF-α)." (PMID 36362727, 2022). "In vivo studies with L. chagasi suggested infection-mediated upregulation of TLR-2 and TLR-4 along with increased expression of IL-17, TNF-α, and IFN-γ during early hours of infection." (PMID 35531875, 2022). "In this study a significant increase in gene expression of TNF-α and Ang II in P2X4/ HCV cells was observed in comparison to NV/HCV cells on day 9 post infection." (PMID 35594248, 2022). "EFTUD2 and SNRNP200 are thus required for induction of necroptosis during MRV infection while EFTUD2’s importance for necroptosis appears to be generalized to other necroptotic stimuli, such as zVAD-fmk/TNFα." (PMID 36560714, 2022). "MCs degranulate and release cytokines (IFN-α and TNFα), chemokines (CCL5, CXCL10 and CXCL12) and proteases that play a critical role in the recruitment of CD8+ T, CD4+ T, NK and NKT cells to the site of infection." (PMID 36466818, 2022). "The level of lung and circulating TNF-α and IFN-γ was over five-fold higher for aEV- than for vEV-treated or control mice after 30 days of infection." (PMID 35295759, 2022). "Another sign of rising infection can be a rise in specific infection laboratory factors, such as PCT, Interleukin 6, TNF alpha (tumour necrosis factor), and others." (PMID 36013534, 2022). "At the acute stage of the infection, we noticed a predominantly Th1 immune response characterized by a high level of serum IFN- γ, TNF-α, and IL-17 and the increased gene expression of IFN- γ, MIP-1α and IP-10 in the liver of infected-untreated mice." (PMID 35446855, 2022). "This suggests that during the bacterial challenge the TNF response is already maximally suppressed before any further CAP activation, such as post-infection application of the ultrasound stimulus." (PMID 35784337, 2022). "Our findings demonstrated decreased expression and secretion of IL8, IL6 and TNFα, while CXCL5, PAI-1 and IFNα remained unaffected even 12 hours post-infection." (PMID 36389723, 2022). "The expression levels of TNF-α protein expression in the duodenum, jejunum and cecum showed that compared with the blank control group, TNF-α protein expression in the infection group was significantly increased." (PMID 35692296, 2022).
infection (continued). "The other notable findings in our agarose bead inoculum experiment were the significantly elevated levels of IL-1α and TNFα in IFT88 KO mice relative to control mice at day 15, with the difference still present and significant at day 54 after infection." (PMID 36505420, 2022). "High TNF-α in SE6 and SE7 indicate that within 4 weeks of being housed with transmitters TR1 and TR2, respectively, the sentinels produce TNF-α to contain the infection." (PMID 36051240, 2022). "A 2-fold increase of Treg cell percentages in TNFR1-/- mice was also consistent with reports from other models, which have shown that excessive TNF signals through TNFR2 enhances Treg cell differentiation and function in inflamed tissues during infection." (PMID 35479068, 2022). "For both strains of Coxiella, there was little secretion of tumor necrosis factor alpha (TNF-α), IL-1β, and IFN-γ, which have been shown previously to control infection." (PMID 35913176, 2022). "ELISA indicated that the levels of the serum cytokines TNF-α, IL-1β, IFN-γ, IFN-β and IL-6 in chickens were significantly higher at 7 dpi after infection with IBV than in the control." (PMID 35909955, 2022). "Tumor necrosis factor-α (TNF-α) is an inflammatory cytokine produced by macrophages and is responsible for inflammation, immunity, and important for resistance to infection and cancers." (PMID 35268699, 2022). "Compared with PCV2 infection alone, coinfection of PCV2 and PRV decreased the expression levels of the TNFα gene." (PMID 35457287, 2022). "A day later the pathways were activated by infection with SeV (for IRF3), or addition of IFN-α (for ISRE) or TNF-α (for NF-κB) and the luciferase activity was measured compared to empty vector (EV) control." (PMID 36478862, 2022). "In contrast to what was observed with intravenous infection, we observed that after 7 days of intratracheal infection, AMΦ from BALB/c mice showed higher production of NO, TNF-α, and IL-10 than AMΦ from Swiss mice." (PMID 36520787, 2022). "For instance, in one study, these two mice lineages were used for obtaining mice defective in TNF-α and IFN-γ and to study the implication of these two molecules in the formation of granuloma upon M. tuberculosis infection and control of the infection." (PMID 36678397, 2022). "DMF treatment after infection with HK‐MRSA, which is termed posttreatment, also suppressed the production of IL‐6 and TNF‐α." (PMID 36354099, 2022). "The naïve infection control group showed the highest levels of TNF-α, IL-6, IFN-γ, and IL-1β cytokines in airway BALF and lung samples at 5 days after infection." (PMID 36146461, 2022). "A lower percentage TNF-α and a higher percentage of IL-17A of Vδ2 subset were observed in HIV/TB group than that in HIV mono-infection." (PMID 36619740, 2022). "Th cells, which are CD4+ T cells, play an important role in protecting the body from infection and secrete both proinflammatory cytokines (e.g., IFN-γ, TNF-α, and IL-6) and anti-inflammatory cytokines (e.g., IL-10)." (PMID 35001010, 2022). "Compared to infection in IMM alone, there was a significant increase in TNFα observed when the epithelia were co-cultured with M1 macrophages in IMM or in M1 medium." (PMID 36228018, 2022). "Surprisingly, despite higher CFUs and neutrophils within C3aR−/− lungs and BALF, respectively, C3aR−/− and WT had the same level of inflammatory cytokines (IL-6, TNF, or IFNγ) within the BALF throughout the duration of infection." (PMID 35925892, 2022). "Quantitative analysis revealed significant levels of the pro-inflammatory cytokines TNFα, IFNγ, and CXCL10 at day 6 after Att-S74-T3Bo infection compared to uninfected control animals." (PMID 36466866, 2022). "Four strains with the highest viral copy numbers (n = 4) and three strains with the lowest viral copy numbers (n = 3) were selected to evaluate TNF-α, IL-6, IFN-β, ISG-15, IFITM1, and TRIM22 expression levels at 6 h post-infection." (PMID 36146585, 2022).